GATAD1 (GATA zinc finger domain containing 1)
Description:
Component of some chromatin complex recruited to chromatin sites methylated 'Lys-4' of histone H3 (H3K4me), with a preference for trimethylated form (H3K4me3).
Synonyms: ODAG; RG083M05.2; FLJ22489; CMD2B
Tractability: PROTAC: UniProt records ubiquitination sites on it.
Gene: Protein-coding gene on chromosome 7 (92,447,482 to 92,460,075, forward strand). Ensembl gene ENSG00000157259.
Subcellular location: Nucleus
Subcellular location (Human Protein Atlas): Nucleoplasm
Gene Ontology:
Molecular function: sequence-specific DNA binding; zinc ion binding
Biological process: chromatin remodeling; chromatin organization; regulation of DNA-templated transcription
Cellular component: nucleoplasm; nucleus
Genetic constraint (gnomAD): Loss-of-function variants: 3 observed, 3.54 expected, observed/expected ratio (o/e) 0.85, 90% interval 0.38 to 1.79. That is too few expected variants to judge how well the gene tolerates losing a copy. Missense variants: 94 observed, 74.99 expected, observed/expected ratio (o/e) 1.25, 90% interval 1.06 to 1.49. Synonymous variants: 47 observed, 33.17 expected, observed/expected ratio (o/e) 1.42, 90% interval 1.12 to 1.79.
Gene-disease validity (ClinGen):
ClinGen rates the evidence that GATAD1 causes each of these diseases.
dilated cardiomyopathy 2B (autosomal recessive): Limited.
Homologues: Orthologues: chimpanzee GATAD1 (99% identical), macaque GATAD1 (99% identical), dog GATAD1 (98% identical), pig GATAD1 (98% identical), rabbit GATAD1 (96% identical), mouse Gatad1 (93% identical), rat Gatad1 (82% identical), tropical clawed frog gatad1 (78% identical), zebrafish gatad1 (74% identical), guinea pig Gatad1 (46% identical), Drosophila melanogaster CG13367 (38% identical).
Diseases named in the same sentence as GATAD1 in open-access papers:
GATAD1 is named in the same sentence as 13 diseases in open-access papers, as found by Europe PMC text mining. Sharing a sentence is not in itself a finding about the gene and the disease. The quoted sentences say what the papers report.
dilated cardiomyopathy (4 papers, 2016 to 2024). Cardiomyopathy which is characterized by dilation and contractile dysfunction of the left and right ventricles. "We further show that a phosphorylation site in the transcription factor GATAD1 that is mutated in a family of patients with dilated cardiomyopathy binds 14-3-3 proteins." (PMID 38605029, 2024). "We focused on a mutation of a serine phosphorylation site in the transcription factor GATAD1, which causes dilated cardiomyopathy." (PMID 38605029, 2024). "GATAD1 is expressed in ventricular myocytes, and mutations in this gene cause dilated cardiomyopathy, a disease characterized by excessive enlargement of cardiac ventricles." (PMID 35588128, 2022).
heart failure (3 papers, 2011 to 2020). Inability of the heart to pump blood at an adequate rate to meet tissue metabolic requirements. "The subcellular localization suggests future research directions to investigate Gatad1 as both a candidate transcription factor and sarcomeric protein, and uncover the pathogenic mechanism by which it leads to heart failure in DCM." (PMID 28955713, 2016).
cardiomyopathy (1 paper, 2016). A disease of the heart muscle or myocardium proper. "We used GATAD1, a recently identified gene for autosomal recessive DCM, as a paradigm to explore adult zebrafish as an in vivo model to validate cardiomyopathy gene mutations with age-dependent penetrance." (PMID 28955713, 2016). "The fact that phenotypes only show up in aged fish models is likely because of the late-onset nature of GATAD1-based cardiomyopathy." (PMID 28955713, 2016).
glioblastoma (1 paper, 2023). The most malignant astrocytic tumor (WHO grade IV). "Four candidate transcription factors (GATAD1, TEAD4, IRF1, and EGR2) were finally obtained and were found to be considerably highly expressed in specimens of patients with glioblastoma according to the results of qRT‐PCR and western blot." (PMID 36987665, 2023).
glioma (1 paper, 2019). A benign or malignant brain and spinal cord tumor that arises from glial cells (astrocytes, oligodendrocytes, ependymal cells). "In this study, we characterized that, by targeting CCND1, GATAD1 gene amplification is associated with GATAD1 overexpression and glioma progression." (PMID 31286678, 2019). "The multivariate and univariate analysis results based on our glioma patients and the TCGA glioma database showed that GATAD1 is a novel glioma prognosis risk factor independent to WHO grades, age, IDH mutation condition and other clinical factors." (PMID 31286678, 2019). "In our 187 glioma samples, we evaluated significant GATAD1 gene copy amplification in WHO grade II‐IV patients." (PMID 31286678, 2019). "The MTT and orthotopic tumor transplantation assays were used to identify the function of GATAD1 in glioma proliferation." (PMID 31286678, 2019). "More importantly, we found that the incidences of GATAD1 amplification were correlated with the glioma grade." (PMID 31286678, 2019). "We used cDNA microarray to screen the downstream gene of GATAD1 and found that CCND1 is the main target of GATAD1 in glioma cells." (PMID 31286678, 2019). "GATAD1 gene amplification and expression were analyzed in 187 gliomas using qPCR and immunostaining." (PMID 31286678, 2019). "We further detected the GATAD1 protein level in our glioma samples using IHC staining, the results indicated that GATAD1 LI (%) was increased in high‐grade glioma." (PMID 31286678, 2019). "In summary, we identified that GATAD1 gene copy amplification induced GATAD1 overexpression and played an oncogenetic role in patients with glioma." (PMID 31286678, 2019). "cDNA microarray, ChIP qPCR, EMSA and 3C were used to screen the downstream mechanism of GATAD1 regulating glioma proliferation." (PMID 31286678, 2019). "In this manuscript, we identified copy number amplification of GATA zinc finger domain containg 1 (GATAD1) in glioma tissues." (PMID 31286678, 2019). "Functionally, we confirm GATAD1 as an epigenetic chromatin topological regulator that promotes glioma proliferation by targeting CCND1." (PMID 31286678, 2019). "Our results indicated that GATAD1 gene amplification and GATAD1 gene expression are novel independent diagnosis biomarkers to indicate poor outcome of glioma patients." (PMID 31286678, 2019). "We also revealed a novel mechanism of glioma malignance driven by GATAD1 by sequentially inducing histone acetylation, chromatin conformation interaction and transcription of CCND1 gene." (PMID 31286678, 2019). "The mRNA level of GATAD1 from TCGA also correlated with the glioma grade; liner regression results further showed positive correlation between mRNA level and GATAD1 copy number in TCGA dataset (r = 0.5392, P < 0.001)." (PMID 31286678, 2019). "We identify GATAD1 as a novel potential diagnosis biomarker and promising prognosis predictor in glioma patients." (PMID 31286678, 2019). "IHC detection of GATAD1 protein expression in our 187 glioma patients’ tissue samples showed that GATAD1 was overexpressed in 69.2% of glioma patients." (PMID 31286678, 2019). "In this study, we showed that GATAD1 gene copy number amplification frequently occurred in glioma tissues and GBM cell lines, this gene amplification leads to overexpression of GATAD1 gene in the tumor tissue compared to normal brain tissue." (PMID 31286678, 2019). "The GATAD1 shRNA transfection significantly inhibited the proliferation of glioma cell." (PMID 31286678, 2019). "GATAD1 gene amplification and overexpression could be a promising prognosis factor for all grades of glioma patients." (PMID 31286678, 2019). "To date, the relationship between GATAD1 amplification and glioma oncogenesis and malignancy is still unknown." (PMID 31286678, 2019). "Furthermore, in our 187 glioma samples, the patients with higher GATAD1 IHC stating level had shorter survival times (median of GATAD1 LI = 31.2%)." (PMID 31286678, 2019).
glioma (continued). "Kaplan‐Meier assay was performed to evaluate the effect of GATAD1 on glioma patients’ outcome." (PMID 31286678, 2019). "High GATAD1 level was dramatically correlated to high glioma grade." (PMID 31286678, 2019). "Univariate and multivariate survival analysis showed that amplification and expression level of GATAD1 were independent predictors of poorer survival of glioma patients, which provided a strong rationale for focusing on GATAD1 in malignant glioma diagnosis and therapy." (PMID 31286678, 2019). "The mechanism of GATAD1 amplification promoting glioma cell proliferation was mediated by CCND1." (PMID 31286678, 2019). "In our glioma samples (WHO grade II‐V) and TCGA glioma sample (LGG + GBM), the patients bearing GATAD1 gene amplification had shorter survival time (DFS and OS)." (PMID 31286678, 2019). "In our glioma samples and TCGA LGG + GBM database, the GATAD1 expression was upregulated in up to 65% of patients, which is slightly higher than the gene copy amplification rate." (PMID 31286678, 2019). "In this study, we found that GATAD1 could directly target the CCND1 gene, promoting CCND1 transcription and accelerating glioma cell G1–S cycle transition." (PMID 31286678, 2019). "For now there is no publication regarding GATAD1 expression and function in gliomas." (PMID 31286678, 2019).
hepatocellular carcinoma (1 paper, 2021). A malignant tumor that arises from hepatocytes. "Additionally, Gatad1 was found to modulate PI3K/Akt signaling activity in hepatocellular carcinoma cells through upregulation of phosphatase of regenerating liver 3 (PRL3) by binding its promoter." (PMID 33921306, 2021).
idiopathic dilated cardiomyopathy (1 paper, 2016). Decreased function of the heart associated with cardiac enlargement and congestive heart failure, of unknown cause. "Interestingly, GATAD1 is highly overexpressed in female idiopathic dilated cardiomyopathy (IDCM) patients comparing to male patients, suggesting GATAD1 might contribute to gender difference in DCM patients." (PMID 28955713, 2016).
Sepsis (1 paper, 2024). Sepsis is defined as life-threatening organ dysfunction caused by a dysregulated host response to infection. "In this study, we aimed to elucidate the role of circ-Gatad1 in sepsis induced AKI and its potential mechanism of action." (PMID 38443846, 2024). "Taken together, our results show that circ-Gatad1 promoted LPS-induced HK2 cell injury via regulating the miR-22-3p/TRPM7 signaling pathway, suggesting that circ-Gatad1 knockdown might be a potential pathway for alleviating sepsis-induced AKI." (PMID 38443846, 2024). "Mechanistically, the regulatory function of circ-Gatad1/miR-22-3p/mRNA network was explored, which might provide a new perspective for the pathogenesis of sepsis-related AKI." (PMID 38443846, 2024).
tumor (2 papers, 2019 to 2025). "The xenograft tumor samples were further detected using IHC for GATAD1 protein level; the results further confirmed that GATAD1 staining signals were weaker in the smaller GATAD1‐sh1/2 xenografts (lower panel GATAD1)." (PMID 31286678, 2019). "Abnormal activation of GATAD1 and ILF2 was associated with invasive tumor characteristics." (PMID 41430036, 2025). "The results showed that knocking down of GATAD1 could inhibit GBM tumor growth in vivo." (PMID 31286678, 2019). "To identify the downstream gene of GATAD1 tumor promoting function in GBM cells, we performed the cDNA microarray among scramble control U87MG cells (control) and GATAD1 knockdown U87MG cells (GATAD1‐sh1/2)." (PMID 31286678, 2019).
GATAD1 also shares sentences with these, for which no sentence is quoted: craniopharyngioma (1 paper); Gaucher disease (1); malignant glioma (1); myoclonic epilepsy (1).